P4HA1 (prolyl 4-hydroxylase subunit alpha 1)
Diseases named in the same sentence as P4HA1 in open-access papers (continued):
Sharing a sentence is not in itself a finding about the gene and the disease.
pancreatic cancer (21 papers, 2016 to 2025). "P4HA1 is also associated with the glucose metabolism in pancreatic cancer cells (PDAC), where it can enhance the Warburg effect and tumor growth in PDAC." (PMID 39021802, 2024). "All these findings showed that P4HA1 was associated with poor prognosis in patients with pancreatic cancer." (PMID 33415167, 2020). "Additionally, a brief model diagram involving the potential mechanism of P4HA1 underlying the progression of pancreatic cancer was drawn." (PMID 33415167, 2020). "Moreover, this study found that high expression of P4HA1 was associated with poor clinicopathological features in pancreatic cancer." (PMID 33415167, 2020). "Expression of P4HA1 in pancreatic cancer was demonstrated to be dependent on HIF1α and to correlate with hypoxia gene signatures, and glycolysis." (PMID 39966387, 2025). "P4HA1 in turn enhanced HIF1α stability, indicating a positive feedback loop between HIF1α and P4HA1 in pancreatic cancer." (PMID 39966387, 2025). "Taken together these results shed light on P4HA1 function in PDAC stroma as a molecular player of stroma deposition in pancreatic cancer development upon metabolic syndrome, ultimately suggesting hydroxyproline levels as potential PDAC biomarkers." (PMID 39828692, 2025). "Recent studies have identified P4HA1 as an oncogene in pancreatic cancer, where it contributes to tumor progression and poor clinical outcomes." (PMID 41080752, 2025). "This study demonstrates that hypoxia increases invasion across a cohort of human pancreatic cancer organoids and identifies the collagen-modifying enzyme P4HA1 as a driver of hypoxia-enhanced invasion." (PMID 40332386, 2025). "Previous studies have elucidated the function and operational process of P4HA1 in colon cancer, gliomas, lung cancer, prostate cancer, and pancreatic cancer." (PMID 39568592, 2024). "Previous studies have demonstrated that P4HA1 plays a significant role in the pathogenesis of pancreatic cancer." (PMID 39568592, 2024). "Further experimental results showed that P4HA1 can increase the stability of HIF1α to form a positive feedback loop, which is a critical regulator in glycolysis and oncogenic activities of pancreatic cancer." (PMID 35651786, 2022). "Among them, the mRNA levels of ADM, C4orf3, ERO1L, FUT11, BNIP3L, NDRG1, KCTD11, SLC2A1, and P4HA1 were increased in pancreatic cancer tissues compared to adjacent pancreatic tissues from TCGA and GTEx database." (PMID 34221996, 2021). "In pancreatic cancer, P4HA1 can promote glycolytic and malignant phenotypes through the P4HA1/HIF1α feedback loop and in ovarian cancer, P4HA1 promotes tumor metastasis by regulating the epithelial-mesenchymal transition (EMT)." (PMID 33952718, 2021). "Three online databases including Sangerbox and GEPIA were used to further evaluate the prognostic value of P4HA1 in human pancreatic cancer." (PMID 33415167, 2020). "In pancreatic cancer, P4HA1 not only was highly expressed but also was related to prognosis in patients." (PMID 33415167, 2020). "This suggests that there was remarkable expression of the P4HA1 protein in pancreatic cancer tissues." (PMID 33415167, 2020). "Results of the GEPIA database analysis similarly indicated that the high expression of P4HA1 indicated poor prognosis in pancreatic cancer patients [OS: HR = 1.6, P = 0.031; DFS: HR = 1.7, P = 0.014]." (PMID 33415167, 2020). "In this study, a set of bioinformatics tools were used to analyze the expression of P4HA1 and its prognostic value in pancreatic cancer." (PMID 33415167, 2020). "The findings showed that the expression pattern of 10 Hub genes was consistent with that of P4HA1 in pancreatic cancer." (PMID 33415167, 2020). "In order to better understand the potential function of P4HA1 in pancreatic cancer, genes coexpressed with the P4HA1 were predicted." (PMID 33415167, 2020). "Identifying genes coexpressed with P4HA1 would help to better understand the potential function of the protein in pancreatic cancer." (PMID 33415167, 2020).
pancreatic cancer (continued). "The study then sought to further verify the correlation between expression of P4HA1 and prognosis of pancreatic cancer." (PMID 33415167, 2020). "It was found that the mRNA and protein expression of P4HA1 was significantly higher in pancreatic cancer tissues than in normal tissues." (PMID 33415167, 2020). "All in all, the findings show that P4HA1 is a reliable and promising biomarker of pancreatic cancer." (PMID 33415167, 2020). "Subsequently, the prognostic analysis revealed that high expression of P4HA1 was related to poor prognosis in patients with pancreatic cancer." (PMID 33415167, 2020). "In order to further explore the mechanism of P4HA1 in the prognosis of pancreatic cancer, the potential mechanism of noncoding RNA regulating P4HA1 was explored." (PMID 33415167, 2020). "In summary, the study utilized bioinformatics tools to provide a reliable, comprehensive analysis of the expression pattern, prognostic value, and potential regulatory mechanism of P4HA1 in pancreatic cancer." (PMID 33415167, 2020). "LINC01503/miR-335-5p/P4HA1 may mediate the action of P4HA1 in promoting pancreatic cancer progression." (PMID 34680441, 2021). "Therefore, in order to explore the potential regulatory mechanism of P4HA1 in the progression of pancreatic cancer, a lncRNA-miRNA-mRNA interaction network was constructed." (PMID 33415167, 2020). "In addition, the potential regulatory mechanism of P4HA1 in promoting the progression of pancreatic cancer was explored by constructing a ceRNA regulatory axis." (PMID 33415167, 2020). "This provided a basis for further analysis of the relationship between P4HA1 and pancreatic cancer." (PMID 33415167, 2020). "P4HA1 can be used as a novel and promising prognostic biomarker for patients with pancreatic cancer, and it may provide a new therapeutic direction for the treatment of pancreatic cancer." (PMID 33415167, 2020). "The LINC01503/miR-335-5p/P4HA1 axis might mediate the effects of P4HA1 in promoting the progression on pancreatic cancer." (PMID 33415167, 2020). "Collectively, our findings suggest that high expression of P4HA1 may be used as a promising prognostic biomarker and could be considered for the development of a novel therapeutic strategy for pancreatic cancer in the future." (PMID 33415167, 2020). "In addition, the mechanism through which P4HA1 promotes the progression of pancreatic cancer was explored by constructing a competing endogenous RNA (ceRNA) regulatory axis." (PMID 33415167, 2020). "Additionally, a ceRNA regulatory axis was constructed to explore the potential mechanism of P4HA1 in the progression of pancreatic cancer." (PMID 33415167, 2020). "P4HA1 was markedly overexpressed in most tumors, especially in kidney and pancreatic cancers." (PMID 33415167, 2020). "Therefore, the expression and clinical value of P4HA1 in pancreatic cancer were comprehensively analyzed in this study." (PMID 33415167, 2020). "In addition, the HPA database confirmed that the level of the P4HA1 protein in pancreatic cancer was higher than that in normal pancreatic tissues." (PMID 33415167, 2020). "However, the association between P4HA1 and pancreatic cancer as well as its role in the progression of the tumor was not clearly shown." (PMID 33415167, 2020). "Therefore, the results suggested that PGK1, ALDOA, and LDHA may play important synergistic roles for P4HA1 in pancreatic cancer." (PMID 33415167, 2020). "However, it was unclear whether P4HA1 plays an important role in the occurrence and malignant progression of pancreatic cancer, which was worthy of further exploration." (PMID 33415167, 2020). "Therefore, the results suggested that these coexpressed genes might play an important synergistic role with P4HA1 in the progression of pancreatic cancer through glycolysis, HIF-1α, and metabolism." (PMID 33415167, 2020). "The P4HA1/HIF1 has been identified as a modulator of glycolysis and carcinogenic activity in pancreatic cancer." (PMID 37903487, 2024).
pancreatic cancer (continued). "Moreover, the mechanism of the ceRNA of P4HA1 affecting the malignant progression of pancreatic cancer has not been reported." (PMID 33415167, 2020).
glioma (19 papers, 2017 to 2025). A benign or malignant brain and spinal cord tumor that arises from glial cells (astrocytes, oligodendrocytes, ependymal cells). "Various reports have linked the P4HA1 gene to cancer proliferation and hypoxic up-regulation, and overexpression has been reported in gliomas and HNSCC; expression has also been linked to tumour micro-vessel density." (PMID 37048688, 2023). "In glioma, P4HA1 protein was found up-regulated, and downregulation of P4HA1 associated with extended OS of xenograft mice." (PMID 34659558, 2021). "Previous research has shown that P4HA1 is a predictive marker for both oral squamous cell carcinoma and high‐grade glioma." (PMID 37903487, 2024). "P4HA1 also enhances glioma neovascularization by facilitating the transition of glioma stem cells into ECs and the formation of vascular basement membrane." (PMID 38238754, 2024). "Bioinformatic analysis results based on the TCGA and GTEx database revealed that P4HA1 overexpressed in glioma compared with normal tissues and high expression of P4HA1 correlated with poor overall survival (OS)." (PMID 35494018, 2022). "Results showed that the expression level of CD31 was higher in glioma samples with high P4HA1 expression, which connote that the expression of P4HA1 in glioma positively correlated with vascular density." (PMID 35494018, 2022). "Analysis of the TCGA database showed that P4HA1 was more highly expressed in glioma than in normal tissues." (PMID 35494018, 2022). "Consistently, this finding was also observed that P4HA1 upregulated the level of classical vascular factors CD31 in the mouse glioma model." (PMID 35494018, 2022). "We screened this series of differentially expressed proteins, comprehensively analyzed the proteins whose molecular functions were related to angiogenesis and co-expressed with P4HA1 in glioma tissues, and finally identified COL6A1." (PMID 35494018, 2022). "The authors also showed the co-expression of P4HA1 and CD31 in endothelial cells within blood vessels in human glioma specimens, other than a positive correlation between P4HA1 and the blood vessel density." (PMID 36294763, 2022). "GSCs transfected with lentivirus overexpressing P4HA1 yielded larger-sized gliomas than their controls after 7 and 14 d, whereas GSCs transfected with lentivirus shP4HA1 yielded smaller tumors than their controls." (PMID 35494018, 2022). "P4HA1 was reported to play an unfavorable prognostic marker in glioma and promote migration and invasion of glioma by accelerating EMT process." (PMID 34966739, 2021). "Newly reports have verified that P4HA1 plays an essential role in the process of glioma stem cells (GSCs) into endothelial cells (ECs) trans differentiation." (PMID 34659558, 2021). "CBX3 promotes cell proliferation and predicts poor prognosis in glioma, and P4HA1 is a biomarker of unfavorable prognosis in malignant melanomas." (PMID 34221975, 2021). "Knockdown of P4HA1 has been reported to inhibit cancer cell proliferation in vitro and reduce tumor growth in xenograft models of breast and prostate cancer and gliomas." (PMID 32053263, 2020). "In an analysis of 81 human glioma specimens using IHC, the P4HA1 gene stood out: the level of P4HA1 were significantly higher in high-grade gliomas, it correlates with MVD and Ki67." (PMID 28415787, 2017). "P4HA1 also had an effect on collagen IV synthesis and the structural integrity of vascular BMs in glioma." (PMID 28415787, 2017). "In summary, the present study is the first to elucidate the role of P4HA1 on proliferation, migration and tube formation in glioma cells." (PMID 28415787, 2017). "We found that the prolyl 4-hydroxylase subunit alpha-1 (P4HA1) was overexpressed in high-grade gliomas, and that P4HA1 expression was correlated with tumor microvessel density (MVD)." (PMID 28415787, 2017).
glioma (continued). "Furthermore, examination of human glioma specimens revealed a positive correlation between P4HA1 expression and blood vessel density, with endothelial cells in blood vessels co-located with P4HA1 and CD31." (PMID 35494018, 2022). "To verify whether P4HA1 can promote glioma angiogenesis, we induced GSCs to transdifferentiate in vitro to simulate angiogenesis in vivo." (PMID 35494018, 2022). "Knockdown of P4HA1 inhibits neovascularization under hypoxic conditions and disrupts the vascular basement membrane, suggesting a relationship between P4HA1 and angiogenesis in glioma." (PMID 35494018, 2022). "Since P4HA1 was closely related to neovascularization, to investigate whether P4HA1 is concerned with vascularization in glioma, we analyzed the co-expression of P4HA1 and angiogenesis-related genes in the TCGA database." (PMID 35494018, 2022). "As increment of blood vessels quantity in glioma denote pathological grade deterioration, we speculated that P4HA1 might be involved in the process of glioma angiopoiesis in the malignant progression of glioma." (PMID 35494018, 2022). "Overexpressed P4HA1 relates closely tumor cell proliferation and angiogenesis in glioma." (PMID 34659558, 2021). "In high-grade gliomas, high expression of P4HA1 was correlated with aggressiveness." (PMID 32166002, 2020). "In glioma, P4HA1 promotes the transdifferentiation of glioma stem cells into endothelial cells leading to the formation of vascular basement membranes and has been considered as a prognostic marker for high-grade glioma." (PMID 32500033, 2020). "In gliomas, overexpression of P4HA1 facilitated neovascularization by transdifferentiating glioma stem cells to endothelial cells and stabilization of vascular base membranes, which contributed to tumor progression and predicted poor prognosis of gliomas." (PMID 33299876, 2020). "Hu et al16 reported that high P4HA1 expression is correlated with the malignancy of gliomas and could serve as a prognostic indicator for patients with high‐grade gliomas." (PMID 31782831, 2020). "Also in other cancers, such as gliomas and prostate cancer, P4HA1 staining has mostly been reported in the tumor cells." (PMID 32053263, 2020). "In human gliomas, we first demonstrated that downregulation of P4HA1 could significantly suppress the proliferation and migration of GSCs during hypoxia in vitro." (PMID 28415787, 2017). "Additionally, knockdown of P4HA1 inhibited the synthesis of collagen IV, and hence disrupted the structures of vascular basement membranes (BMs) in gliomas." (PMID 28415787, 2017). "Taking all of these findings into account, we may conclude that knockdown of P4HA1 disrupts the integrity of tumor vessels via suppression of the collagen IV formation in glioma." (PMID 28415787, 2017). "Altering the expression of P4HA1 in GSCs altered the expression of COL6A1 and CD31, thereby inducing glioma angiogenesis." (PMID 35494018, 2022). "The knockdown of P4HA1 has also been found to inhibit the synthesis of COL‐IV and disrupt the structures of vascular basement membranes in glioma xenografts." (PMID 32053263, 2020). "We determined that P4HA1 expression was correlated with histological grade, the level of Ki67 and microvessel density (MVD) in human glioma specimens." (PMID 28415787, 2017). "The study also has some limitations on whether P4HA1 and COL6A1 can promote angiogenesis in other type tumors like glioma remains to be defined." (PMID 35494018, 2022). "P4HA1 was localized to the cytoplasm and was expressed in high-grade gliomas compared to low-grade gliomas, and a significant difference in P4HA1 expression was observed between WHO III and IV grade gliomas." (PMID 28415787, 2017). "For instance, PGK1 promotes glycolysis-driven aggressiveness in gastric and colorectal cancers; P4HA1 regulates collagen remodeling and hypoxia adaptation in breast and lung cancers; and SLC7A11/xCT contributes to ferroptosis resistance in pancreatic, glioma, and prostate cancer models." (PMID 41562911, 2025).